FOXP3 (forkhead box P3)
Diseases named in the same sentence as FOXP3 in open-access papers (continued):
Sharing a sentence is not in itself a finding about the gene and the disease.
tumor (continued). "Furthermore, a recent study showed that vaccination of mice with Fox–Fc DNA vaccine/recombinant FOXP3–Fc fusion protein induced a CTL response against FOXP3+ T-regs, which decreased tumor growth and prolonged survival rates." (PMID 31547627, 2019). "Finally, tumor size, degree of differentiation, TNM stage, Lgr5 expression level, and intratumor FoxP3+ Tregs were included in a multivariate Cox proportional hazards analysis." (PMID 31417548, 2019). "Namely, the presence of tumor infiltrating CD3+CD8+FoxP3− T cells, galectin-9+ dendritic cells (DC)/DC-like macrophages, a high CD14+CD163− (M1)/CD14+CD163+ (M2) macrophage ratio, and the expression of galectin-3 by tumor cells." (PMID 31248118, 2019). "In addition, immunohistochemistry staining of the tumor tissues showed that the expression of DR4 and DR5 was increased, while the expression of FoxP3 was decreased significantly in CPP treatment group." (PMID 31864387, 2019). "Next, we assessed the size and cell composition of IAs by counting cells of 6 different sub-types (all tumor cells, HLA+ tumor cells, CD3+, CD4+ FOXP3+, CD8+PD1+, CD20+ cells) and calculated counts of each of these subpopulations relative to the number of total tumor cells in IAs." (PMID 31166985, 2019). "In fact, higher numbers of CD8+ cells could be observed per gram of tumor tissue, whereas FOXP3−CD4+ and FOXP3+CD25+CD4+ Tregs cells decreased." (PMID 31046839, 2019). "Not only did we detect high numbers of CD4+ T cells co-expressing both the transcription factors Foxp3 and Tbet in these HPV16-driven tumors but we also found that their numbers are directly related to the number of tumor-infiltrating type 1-oriented (Foxp3-) effector T cells." (PMID 30658697, 2019). "However, no statistically significant multivariable adjusted correlations were observed between platelet count and the densities of tumor infiltrating CD3+, CD8+, and FoxP3+ T cells, neutrophils, or mast cells." (PMID 31196200, 2019). "Comparing to brisk TIL areas, tumor with non-brisk TIL areas contained more HLA-1 negative tumor cells and immunosuppressive cells, such as FOXP3+ T cells." (PMID 31166985, 2019). "Tumor inhibition in mice immunized with mD8-FAT1-OMVs was accompanied by the accumulation of infiltrating CD8+ and CD4+ T cells and by the concomitant reduction of regulatory T cells (CD4+/Foxp3+) and myeloid-derived suppressor cells (MDSCs)." (PMID 30416985, 2018). "However, mice bearing tumor and treated with L. casei BL23 exhibited significantly higher local Foxp3 level." (PMID 30687269, 2018). "Here, we performed comprehensive immunohistochemical analysis of the local tumor infiltration level of CD4 +, CD8 +, and Foxp3 + T lymphocytes and of PD-L1 expression on tumor cells in resected specimens of eCCA, and we further analyzed their association with EMT-related protein expression." (PMID 29732001, 2018). "While in the infiltration with CD3+, CD8+, or FOXP3+ cells in the tumor center did not affect survival, CD8+ T cell infiltration in the tumor stroma and at the invasive margin correlated with an increased patients’ survival." (PMID 29495308, 2018). "In this study, we found that there were positive correlations between the expression of ST2 and FOXP3, CD11B, and CD33, indicating that the IL-33/ST2 axis may also regulate the function of Tregs and MDSCs in the tumor microenvironment of STS." (PMID 29896199, 2018). "In addition, we collected serum samples from tumor-bearing mice that were treated with control or FOXP3-overexpressing adenovirus and found that serum VEGF levels were decreased in mice bearing FOXP3-overexpressing tumors." (PMID 29970908, 2018). "These markers (Foxp3, CD68, and CD163) were expressed on immune cells in the tumor stroma." (PMID 29506555, 2018). "Many CD8 + T cells infiltrated into the tumor tissue after treatment, whereas no infiltration of FoxP3+ cells was observed." (PMID 29416816, 2018).
tumor (continued). "Across all studied mouse models, CTLA-4 expression appeared higher in the tumor and was largely restricted to CD4+FoxP3+ Treg cells (mean expression 68.3%), relative to CD4+FoxP3− effector (CD4+eff) T cells (10.2%, p < 0.0001) and CD8+ T cells (5.4%, p < 0.0001)." (PMID 29576375, 2018). "Therefore, this study aimed to explore the presence of CD8+ and FoxP3+ infiltrating T cells and TGF-β expression in tumor tissues and analyze their clinical significance." (PMID 30359281, 2018). "It demonstrates the number of FoxP3 positive cells that infiltrated tumor tissues of statins users compared to statins non-users." (PMID 30515267, 2018). "We did not see any marked difference of infiltration of CD4, CD8 or FOXP3 positive cells induced by VQ-1 treatment, indicating that VQ-1 neither increases nor decreases the host anti-tumor immune response." (PMID 29492202, 2018). "Furthermore, we also found that the expression of STAT5 and TET2 were increased in CD4+ T cells from tumor tissues, and the massive STAT5 binds more TET2 to the FOXP3-TSDR and upregulates FOXP3 expression." (PMID 30013992, 2018). "The majority of tumor-infiltrating Treg cells, which express FoxP3, have been detected in GIST rather than non-GIST sarcoma." (PMID 30158830, 2018). "The CD25+CD4+FoxP3+ Treg cells are potent suppressors of antigen-specific or non-specific tumor immunity, with FoxP3 is a master gene that controls the differentiation of CD25+CD4+ T-cell and its functions." (PMID 29535722, 2018). "The differential distributions of CD4+CD25+Foxp3+ Tregs were observed regardless of tumor region, LN metastasis and clinical staging." (PMID 30012191, 2018). "Cancer cell- and M2 macrophages derived SDF-1 attracts Treg cells into the tumor lesion where they robustly induce FOXP3 and other Treg signature molecules in human naïve CD4+ T cells which display enhanced FOXP3 stability and low expression of pro-inflammatory cytokines." (PMID 30622535, 2018). "Using flow cytometry analysis, we thus evaluated the impact of SVX treatment on the frequencies and phenotypes of CD8+ T cells, CD4+ FoxP3− Tconv, and CD4+ FoxP3+ Treg cells both in the spleen and among tumor infiltrating lymphocytes (TILs) of TB mice vaccinated or not with SVX but also in TF mice." (PMID 30483475, 2018). "Elevated CD4+ and CD4+FOXP3+ populations were correlated with shorter recurrence-free survival, and the perivascular CD4+FOXP3+ Treg population in primary tumors was identified as an independent predictor of tumor recurrence in this cohort." (PMID 32914058, 2018). "In the lungs of tumor-bearing mice, it was observed a significant increase in the numbers of CD4+Foxp3+IL-10+ and a significant decrease in ROR-γ+IL-17A+CD4+ T cells T cells in metformin-treated and protected animals, phenotypically similar to Treg and Th17 cells, respectively." (PMID 29899823, 2018). "These selective effects could be due to the permanent tumor-induced proliferation of Tregs, which makes them more sensitive to CTX, or their constitutive Foxp3 expression, which increases the production of proapoptotic molecules." (PMID 29462900, 2018). "Enabling tumor progression, activated CD4+Foxp3+ regulatory T cells (Tregs) are known to migrate to the tumor site and inhibit of CD8 effector T cells (Teffs), which are mainly responsible for anti-tumor immune responses." (PMID 29673141, 2018). "Our data demonstrated that CD25 blockade was efficient in depleting intra-tumor or peripheral FoxP3+ Tregs, but not enhancing CD8+ TIL number and function." (PMID 30359281, 2018). "In order to determine whether anal glandular neoplasms meet this criteria, PD-L1 expression in epithelial (tumour) cells as well as intratumoural CD4+, CD8+, Foxp3+, and PD-1+ T cell densities were analysed by immunohistochemistry." (PMID 29700411, 2018).
tumor (continued). "In this study, we aim to analyze the expression of CD8 and FoxP3 on T lymphocytes and TGF-β expression in tumor tissues, and then analyze the possible clinical significance of these finding in order to find a novel effective immunotherapy target in PDAC using a murine model." (PMID 30359281, 2018). "Animal studies of dendritic cell (DC)-derived exosomes showed improved tumor microenvironment by a significant increase in CD8+ T lymphocytes, elevated levels of IFN-γ and interleukin-2, and decrease in CD25+Foxp3+ regulatory T (Treg) cells and of interleukin-10 and TGF-β in tumor sites." (PMID 30108680, 2018). "In the Kaplan–Meier curve analysis, FoxP3 expression Tregs were significantly considered to be a prognostic factor correlated with OS (p = 0.003), while presence of intra-tumor CD8+ TILs showed no prognostic significance for OS (p = 0.081)." (PMID 30359281, 2018). "Overall, density of tumor-associated macrophages (TAMs; CD68+) was higher in NCT tumors than in non-NCT tumors, and density of memory/regulatory cells (CD45RO + FOXP3+) was lower in the NCT group than in the non-NCT group." (PMID 29871672, 2018). "Tumor-infiltrating Tregs, in particular, CD4+ T cells expressing interleukin-2 receptor chair-alpha (IL2Rα; CD25) and transcription factor forkhead-box P3 (FOXP3), suppress CTL and contribute to a tumorigenic TME." (PMID 29970158, 2018). "There were no significant trends in frequencies of CD3, CD8 or FoxP3 with age at the time of diagnosis, stage of disease, or tumor grade (data not shown)." (PMID 29843813, 2018). "We also found the significant correlation between the expression levels of GZMA and FOXP3 (R=0.68, P=0.001), indicating the activation of immune suppressive system as a negative feedback manner to protect the tumor cells from anti-tumor immunity." (PMID 29423084, 2018). "The principal immune cell populations responsible for tumor destruction are the CD3+ tumor infiltrating lymphocytes (TIL) including helper CD4+ and cytotoxic CD8+ lymphocytes while the principal suppressor cell subset is the FOXP3+ T cells." (PMID 30577521, 2018). "In addition, the activation and cytokine production by both CD4+Foxp3- and CD8+ tumor infiltrating T cells were markedly suppressed." (PMID 29672594, 2018). "We validated that CD3+, CD8+, and FOXP3+ T lymphocytes were indeed more often detected at the surface of stroma than of epithelium compartment, thereby highlighting the potential role of CAF on T lymphocytes infiltration within tumor bed." (PMID 29535360, 2018). "In a cohort of 94 CRC patients, primary tumors (PTs) with corresponding tumor-draining lymph nodes (TDLNs, n = 93) and extranodal/distant metastases (n = 27) were retrospectively analyzed by immunohistochemical staining for IDO, CD8 and Foxp3." (PMID 29861865, 2018). "This review focuses on how the multilayered crosstalk between different Notches and NF-κB subunits may converge on Foxp3 gene regulation and orchestrate CD4+ regulatory T (Treg) cell function, particularly in a tumor microenvironment." (PMID 30364244, 2018). "Although we could not identify the responsible genes that promoted transcription of CCNA1 and CCNA2, we found that positive correlation between FOXP3 as TF and CCNA2 as TG is disrupted in tumor samples." (PMID 29504910, 2018). "While physiologically active, low butyrate amounts in the intestine induce the differentiation of Foxp3+ Tregs, higher concentration of this SCFA might rather promote anti-tumor effects by optimizing the effector function of CD8+ T cells." (PMID 30258117, 2018). "As FOXP3 is instrumental for the suppressive function of Tregs, the relative ability of a-CTLA4-TGFβRII and a-CTLA-4 to counteract Treg-mediated suppression of tumor-reactive T cells was also examined using tumor-infiltrated BM from a patient." (PMID 29467463, 2018).
tumor (continued). "In the tumor-inflammatory microenvironment, we observed a significant increase in the proportion of cytotoxic CD8 + T cells in baicalein-treated mice, a sixfold of the proportion of CD8+/FoxP3+ cells compared to the control group." (PMID 30618763, 2018). "The count of CD4+ Treg cells (CD4+/CD25+/FoxP3+) was lower in the tumor with HOE642 treatment, with no changes of CD4+ T cells and CD8+ T cells." (PMID 30333031, 2018). "Conversely, sunitinib treatment significantly reduced the magnitude of Tregs (CD4+CD25+FoxP3+) from 10% in control tumor-bearing mice without treatment to 7%, and MDSCs (CD11b+Gr-1+) from 1.1% to 0.7%." (PMID 30123861, 2018). "FOXP3 represses the expression of different oncogenes, while overexpression of FOXP3, but not FOXP3ΔGlu251, decreases tumor cell proliferation." (PMID 29593749, 2018). "One strategy for evoking effective tumor immunity without autoimmunity is to specifically target terminally differentiated effector Treg cells rather than all FoxP3 T cells." (PMID 29546043, 2018). "This unexpected finding suggests that, in contrast with other tumor types, Foxp3+ Treg cells do not seem to participate in the induction and maintenance of immune tolerance by tumor cells." (PMID 30546030, 2018). "Since T‐regs numbers increase as a result of tumor progression, we looked at numbers of CD4+, CD25+, FoxP3+ T‐regs to see if the noted increases of CD4+ T‐cells resultant of subcutaneous tumors might be due to an increase in T‐regs." (PMID 28250928, 2017). "Interestingly, microscopic findings showed co‐infiltration of CD4+ and CD8+ lymphocytes in the tumor area in 27 of 36 cases, and CD68+ cells and FoxP3+ cells were diffusely infiltrated in the tumors." (PMID 28602029, 2017). "FoxP3 staining was highly specific with nuclear staining found only in lymphocytes and not in tumor cells." (PMID 28428880, 2017). "At 0 to 5 days in culture without Dox, levels of miR-200c and miR-141 in tumor cells increased as FOXP3 was induced." (PMID 28637482, 2017). "Recently, the expression of FOXP3 has been recently reported in non-hematopoietic derived cells, including normal epithelial cells and some tumor cells from different tissue origins." (PMID 28903735, 2017). "All these information suggest that the FOXP3-expressing CD8+ T cells generated in in vitro tumor microenvironment are not activated CD8+ T cells." (PMID 28487507, 2017). "We observed that in our in vitro generated tumor-microenvironment, CTLA4+ ‘exhausted’ T cells percentage were very low (<1%) as compared to FOXP3+CTLA4+CD8+ Treg cells (6.5%) and this indicated that isolated CD8+CD25+CTLA4+ T cell population predominantly comprised of CD8+ Treg cells." (PMID 28487507, 2017). "Also analyzed were non-tumor draining (brachial, BLN), tumor-draining lymph nodes (inguinal, ILN) and MC32A tumor microenvironment for changes in CD4+ FoxP3+ and proliferative/activated (i.e., Ki67+/CD44+) CD4+FoxP3- and CD8+ effector T cells." (PMID 29088720, 2017). "The tumour tissues were co-stained for Foxp3 and IFN-γ and the Foxp3/IFN-γ ratio was calculated." (PMID 28541302, 2017). "Since, induced FoxP3 are downregulated for CCR7 and CD62L as well as upregulated for memory or effector-type trafficking receptors such as CCR4, CCR5, CCR8, CCR10, and/or CXCR4, they can migrate into the tumor via the tumor-draining lymph nodes." (PMID 29450136, 2017). "Our second finding primarily focuses on the impact of immunologic markers in the tumour microenvironment, specifically how a low percentage of CD8+ lymphocytes, high percentage of Galectin-9+ NPC cells and high percentage of Foxp3+ lymphocytes affect the outcome of recurrent NPC." (PMID 28871094, 2017). "To further understand the role of adaptive immunity in the tumor tissue, we investigated the impact of RRS on tumor weight and on immune suppression markers (Foxp3, CCL22), as well as markers for anti-tumor immunity (Granzyme B, CCL5, IFN-γ, CXCL9, CXCL10 and CXCL11)." (PMID 28603578, 2017).
tumor (continued). "Moreover, deletion of Tgfbr1 and Pten in murine epithelia activated HIF-1α, CD73 and subsequently induced A2AR overexpression in tumor infiltrating immune cells, accumulating immunosuppressive CD4+ Foxp3+ Tregs in the stroma of tumors." (PMID 28592285, 2017). "The percentage of Treg (CD4+/CD25+/FoxP3+) in the tumor was low and irradiation with 2 × 5 Gy induced no higher amounts of Treg when compared to the normal turnover in non-irradiated tumors." (PMID 28337197, 2017). "To visually observe tumor-infiltrating Tregs in xenografts, we detected CD4 and Foxp3 expression to identify Tregs in tissue section of tumors by double immunofluorescence stains, positive expression of Foxp3 was used to locate Tregs cells because CD25 is not specific for these cells." (PMID 28472762, 2017). "Tumor samples and NSCLC cell lines were used to examine FOXP3 and its related molecules." (PMID 28716029, 2017). "To test the effects of beta blockers on the chemokine environment in tumors of RRS-exposed animals, we examined the expression of genes that are characteristic of either immune suppression (Foxp3, CCL22) or effector anti-tumor immunity (Granzyme B, CCL5, IFN-γ, CXCL9, CXCL10 and CXCL11)." (PMID 28603578, 2017). "Tumor-infiltrated CD4+Foxp3+ Tregs highly express CD25, while CD4+Foxp3- cells did not, allowing the anti-CD25-Ce6 complex to specifically target tumor-infiltrated Tregs." (PMID 28537894, 2017). "Finally, the patients with recurrent NPC had a high percentage of Galectin-9+ tumour cells accompanied by a low percentage of CD8+ lymphocytes and high percentages of Foxp3+ and Tim-3+ lymphocytes." (PMID 28871094, 2017). "As we observed a dual role of GATA3 in the regulation of FOXP3 gene expression, we intend to unveil the relative binding of GATA3 in CNS1 and CNS2 region at various stages of CD8+ Treg development in our in vitro tumor model." (PMID 28487507, 2017). "Furthermore, pharmacological blockade of A2AR in vivo by antagonist SCH58261 repressed the tumor growth, inducing a reduction of CD4+ Foxp3+ Tregs and an enhanced anti-tumor response of CD8+ T cells." (PMID 28592285, 2017). "Furthermore, we found no significant reduction in CD8+T cells, whereas the ratio of CD8+T:Foxp3 cells and CD8+T:PD-L1 cells was suppressed in tumor tissues and elevated in adjacent normal tissues." (PMID 29025424, 2017). "Compared with control groups, exendin-4 suppressed subcutaneous tumor growth in a dose-dependent manner, accompanied by increased interferon (IFN)-γ secreting CD8+ cytotoxic T lymphocyte (CTL)/Foxp3+ regulatory T cell (Treg) ratio as well as Th1 proinflammatory cytokines IFN-γ and IL-2." (PMID 28496193, 2017). "In T-cell infiltrated tumors with a signature indicative of active Th1-type response tumor escape is characterized by PD-L1 upregulation, by induction of and infiltration with CD25+FOXP3+Tregs and by T-cell anergy characterized by defective IL-2 secretion upon antigen stimulation." (PMID 28402937, 2017). "Indeed, pharmacological blockade of A2AR by antagonist repressed the tumor growth of 2cKO mice and reduced the population of CD4+ Foxp3+ Tregs." (PMID 28592285, 2017). "We did not observe any significant effect on tumor-infiltrating CD4+FoxP3+ Tregs by any of the treatments compared to the PBS control group." (PMID 28807056, 2017). "IFN-γ+ cells decreased, whereas Foxp3+ cells increased in the tumours composed of lnc-EGFR, but not lnc-EGFRΔR1, -transduced CD4+ T cells." (PMID 28541302, 2017). "The density of CD 4+, CD8+, and FOXP3+ T lymphocyte was not significantly different between tumor response groups." (PMID 29108360, 2017). "PD‐L1 expression correlated with tumor infiltration by CD68+ and FoxP3+ cells." (PMID 28602029, 2017). "In situ FOXP3 analyses revealed only a few regulatory T (Treg) cells, scattered as single cells throughout the tumor, but not concentrated within the main immune infiltrate." (PMID 28967558, 2017).